RN7SL72P (RNA, 7SL, cytoplasmic 72, pseudogene)
Gene: Miscellaneous RNA gene on chromosome 7 (148,438,309 to 148,438,577, forward strand). Ensembl gene ENSG00000243374.
Homologues: Orthologues: chimpanzee Metazoa_SRP (99% identical), macaque Metazoa_SRP (69% identical). Paralogues in human: RN7SL1 (78% identical), RN7SL431P (78% identical), RN7SL2 (78% identical), RN7SL186P (77% identical), RN7SL3 (77% identical), RN7SL386P (77% identical), RN7SL559P (77% identical), RN7SL679P (77% identical), RN7SL45P (76% identical), RN7SL803P (76% identical), RN7SL566P (76% identical), RN7SL320P (75% identical), and 704 more.